IL31 (interleukin 31)
Description:
Functions as a cytokine that binds to IL31RA, a membrane-bound signal-transducing subunit of the IL31 receptor complex (heterodimer composed of OSMR and IL31RA). Functionally, IL31 signaling via OSMR/IL31RA is particularly important in skin immunity. Mechanistically, ligand binding to IL31RA, induces heterodimerization with OSMR, activating JAK1 and JAK2 (and to a lesser extent TYK2) associated with the intracellular domains of IL31RA and OSMR. These kinases phosphorylate tyrosine residues on IL31RA and OSMR, creating docking sites for STAT1, STAT3, and STAT5B, which are then phosphorylated and activated. In addition, the IL31 receptor complex activates the MAPK pathway (MAPK3/ERK1-MAPK1/ERK2) via recruitment of the adapter protein SHC1. Enhances myeloid progenitor cell survival in vitro (By similarity). Induces RETNLA and serum amyloid A protein expression in macrophages (By similarity).
Synonyms: IL-31
Tractability: Antibody: UniProt places it where antibodies can reach, with high confidence; its Gene Ontology location is reachable by antibodies, with high confidence; UniProt predicts a signal peptide or a membrane-spanning region.
Gene: Protein-coding gene on chromosome 12 (122,172,029 to 122,174,221, reverse strand). Ensembl gene ENSG00000204671.
Subcellular location: Secreted
Pathways (Reactome):
Immune System: IL-6-type cytokine receptor ligand interactions
Gene Ontology:
Molecular function: cytokine activity; protein binding; cytokine receptor binding
Biological process: cytokine-mediated signaling pathway
Cellular component: extracellular region
Genetic constraint (gnomAD): Loss-of-function variants: 9 observed, 8.85 expected, observed/expected ratio (o/e) 1.02, 90% interval 0.61 to 1.71. That is too few expected variants to judge how well the gene tolerates losing a copy. Missense variants: 162 observed, 214.76 expected, observed/expected ratio (o/e) 0.75, 90% interval 0.66 to 0.86. Synonymous variants: 87 observed, 91.27 expected, observed/expected ratio (o/e) 0.95, 90% interval 0.8 to 1.14.
Homologues: Orthologues: chimpanzee IL31 (99% identical), macaque IL31 (91% identical), dog IL31 (53% identical), mouse Il31 (28% identical), rat Il31 (28% identical).
Diseases named in the same sentence as IL31 in open-access papers:
IL31 is named in the same sentence as 192 diseases in open-access papers, as found by Europe PMC text mining. Sharing a sentence is not in itself a finding about the gene and the disease. The quoted sentences say what the papers report.
Pruritus (196 papers, 2007 to 2026). Pruritus is an itch or a sensation that makes a person want to scratch. "The primary cytokine associated with burn pruritus is generally considered to be Interleukin-31 (IL-31), often referred to as a key “pruritogen” directly responsible for triggering itch sensations in the skin, burn wounds and wound healing processes." (PMID 39982335, 2025). "IL-31, a T helper 2-derived cytokine known for its role in pruritus, has been implicated in the pathogenesis of PLCA." (PMID 40661111, 2025). "In the mechanistic basis of the IL-33/IL-31 axis, IL-33 initiates inflammation, while IL-31 enhances neurons’ sensitivity, causing pruritus." (PMID 41155460, 2025). "Pruritus, often a predominant symptom in BP even before blistering occurs, is closely linked to IL-31 expression." (PMID 41226755, 2025). "Cytokine dysregulation—particularly increased levels of IL-31, IL-6, and substance P—has been implicated in pruritus pathogenesis, along with neurogenic inflammation and damage to peripheral nerve endings." (PMID 41463055, 2025). "Clinically, elevated IL-4, IL-13, and IL-31 are implicated in the pruritus seen in MF, with IL-31 levels correlating with both disease progression and symptom severity." (PMID 40864740, 2025). "Conversely, nemolizumab targets IL-31, a cytokine directly associated with the development of pruritus in AD." (PMID 39992967, 2025). "It is possible that, similar to HIV associated pruritus, IL-31 is involved in post herpetic pruritus." (PMID 40491521, 2025). "Conversely, psoriasis-associated pruritus involves IL-17-driven neuronal activation and IL-31/OSM signaling, partially overlapping with the BP signature." (PMID 41346997, 2025). "Among the implicated cytokines, IL-13 and IL-31 have been shown to promote the elongation and branching of sensory nerve fibers, thereby intensifying pruritus." (PMID 40364058, 2025). "This case represents the first report of sequential use of difelikefalin and nemolizumab for dialysis-associated pruritus and highlights the need for further studies to evaluate the efficacy of IL-31-targeted therapies in this setting." (PMID 40458322, 2025). "IL-4, IL-13, and IL-31 are implicated in pruritus, offering therapeutic targets with dupilumab, tralokinumab, lebrikizumab, and nemolizumab." (PMID 38398754, 2024). "Interleukin-31 (IL-31) is a cytokine that plays a critical role in the immune system and is closely associated with pruritus." (PMID 39519379, 2024). "Conversely, elevated levels of IL-17 hinder skin repair, while overexpression of IL-31 is linked to pruritus." (PMID 39015574, 2024). "An increase in IL-31 expression in the lesional skin of IBH compared to healthy horses is associated with Th2-mediated pruritus via the IL-31 signaling axis." (PMID 39076967, 2024). "Recently, several cytokines, including TSLP, IL-4/13, and IL-31, have been reported to be involved in AD-associated pruritus, and biological agents targeting these cytokines have been shown to improve pruritus in AD patients." (PMID 38590314, 2024). "Meanwhile, paeonol downmodulated IL-31 levels in the skin of mouse models for AD, while IL-31 has been implicated in inducing pruritus by transmitting pruritus to the central nervous system." (PMID 39588155, 2024). "IL-31 is associated with pruritus in several diseases, including AD psoriasis, cutaneous T-cell lymphoma, stasis dermatitis, bullous pemphigoid, scabies, and primary localized cutaneous amyloidosis." (PMID 38493053, 2024). "A double-blind, randomized, placebo-controlled, phase I/Iib clinical trial using nemolizumab was performed in humans and revealed that the anti–IL-31 antibody improves the clinical symptoms and decreases pruritus associated with AD." (PMID 38672221, 2024). "IL-31, a cytokine implicated in chronic pruritus across various diseases, is also of interest in the context of MF-associated pruritus." (PMID 39068637, 2024).
Pruritus (continued). "Our study focused on investigating ex vivo skin biopsies in AD (n = 17), CNPG (n = 14) and healthy controls (HC; n = 10), examining the gene expression landscape of interleukins linked with pruritus (IL-13, IL-4, IL-31) and their corresponding receptors." (PMID 39126011, 2024). "Th2-mediated IL-31 expression, associated with pruritus, was found to be significantly increased when comparing mild IBH to healthy controls or to moderate/severe IBH." (PMID 39076967, 2024). "In this study, HDM-induced IL-31 by cutaneous lymphocyte-associated antigen (CLA)+ memory T cells correlated with patient’s pruritus." (PMID 36993985, 2023). "It has been suggested that pathogenic mutations in OSMR and IL31RA genes lead to incorrect IL-31 signaling, which is directly related to pruritus." (PMID 38137741, 2023). "Among the up-regulated genes in this group, IL-20 is associated with IL-31-induced barrier disruption, and has also been related with pruritus in murine AD models." (PMID 36993985, 2023). "For example, in both stasis dermatitis and scabies, increased numbers of IL-31-producing M2 macrophages in the lesion have been linked to the severe pruritus in these patients." (PMID 37555911, 2023). "Interleukin 31 (IL-31), a novel cytokine in AD, causes pruritus, typically characteristic of AD patients." (PMID 37686326, 2023). "Interleukin-31 (IL-31) is a T-cell cytokine whose overexpression causes pruritus and dermatitis similar to AD." (PMID 36674561, 2023). "In hemodialysis patients with uremic pruritus and elevated serum interleukin (IL)-31 levels, smoking is associated with moderate to severe pruritus." (PMID 37308936, 2023). "IL-4, IL-13 and IL-31 are implicated in the genesis of pruritus, particularly by their involvement stimulating specific sensitive neurons through a JAK-dependent mechanism; also, IL-31 stimulates sensitive nerve fibers elongation." (PMID 36428493, 2022). "In murine models and patients with atopic dermatitis, the use of an H1R antagonist resulted in a reduction in IL-31 (interleukin-31) levels, which is associated with the onset of pruritus." (PMID 36295796, 2022). "IL-31, a T helper 2 inflammatory cytokine and pruritogen, has been shown to be involved in DM-associated pruritus, with an upregulation of IL-31 in lesioned skin of DM patients with pruritus." (PMID 36012289, 2022). "A higher serum IL-31 level has also been reported to be associated with pruritus intensity in hemodialysis patients." (PMID 35744059, 2022). "Increased TARC can activates Th2 cells to promote the production of pruritus-causing IL-31 and induce the skin to an inflammatory chronic stage." (PMID 36292928, 2022). "Transgenic mice with epidermis overexpressing IL-4 and IL-13 exhibited AD-like symptoms, including skin lesions and pruritus, and both IL-31 transgenic mice and wild-type mice treated with IL-31 developed hallmark features of AD and scratching behavior." (PMID 36232673, 2022). "IL‐31: IL‐31 is associated with pruritus that occurs with AD and plays a pathogenic role in the progress of inflammation." (PMID 35677926, 2022). "It has been reported that IL-13 highly stimulates TRPA1 expression in mast cells and IL-31-induced pruritus decreased in TRPA1-deficient mice." (PMID 35563259, 2022). "IL-31-induced pruritus was reported to be associated with TRPA1 and TRPV1 neurons; however, IL-31-mediated neuronal growth was independent of the TRPV1 channels." (PMID 34281281, 2021). "Despite this variation, IL-31 has been linked with the development of pruritus in multiple mammalian species." (PMID 33644103, 2021). "BP-associated pruritus is also mediated by IL-31 expressing eosinophils, which are a major source of this pruritogenic cytokine in the skin and serum of BP patients." (PMID 33807098, 2021).
Pruritus (continued). "IL-4 and IL-33 are also found to induce the secretion of IL-31, which is one of the elements alongside with the discussed interleukins, causing pruritus in AD and in CTCL—but the data are ambivalent concerning lymphomas." (PMID 34948183, 2021). "Once more, high blood levels of IL-31 were linked to pruritus intensity and serum and tissue expression of the chemokine CCL18." (PMID 34118946, 2021). "The role of IL-31 causing pruritus has been put forward, especially in atopic dermatitis, but also in other skin diseases as ACD." (PMID 35386968, 2021). "More recent findings have demonstrated that nemolizumab, an anti-IL-31RA antibody that binds to IL-31RA with subsequent inhibition of IL-31 signaling effectively relieves AD-associated pruritus." (PMID 33681256, 2021). "A number of researchers observed an association between IL-31 and inflammatory skin diseases with severe pruritus including AD, bullous pemphigoid, cutaneous T-cell lymphoma, CSU and psoriasis." (PMID 33681256, 2021). "Future research is required to answer the details of how IL-31 induces pruritus and causes atopic dermatitis." (PMID 32664385, 2020). "The presence of IL-31 receptors in the spinal cord and brain tissues and its association with pruritus also raises the possibilities that cells of the CNS can produce IL-31 to directly stimulate sensory neurons to mediate the itch." (PMID 32204450, 2020). "The published literature to date shows that IL-31 is differentially associated with autoimmune skin diseases, especially those where pruritus is a major symptom, such as CsU and bullous pemphigoid." (PMID 31281316, 2019). "In an animal model of atopic dermatitis anti-IL-31 treatment significantly reduced scratching in mice, underlining the important role of IL-31 in mediating pruritus." (PMID 31281316, 2019). "Furthermore, M2 macrophages are thought to be one of the cellular sources of IL‐31, which is associated with pruritus in AD, and M2 secretion of IL‐31 is influenced by factors such as IL‐4, M‐CSF released by basophils." (PMID 39654684, 2024). "Indeed, Il-31 which has been established as an important mediator of pruritus has also been found to be associated with poorer sleep quality." (PMID 38291494, 2024). "Moreover, increased IL-31 levels were found in the epidermis and dermal infiltrate of CTCL patients, with epidermal IL-31 levels correlating with itch severity, and reductions in IL-31 levels associated with improvements in pruritus." (PMID 39068637, 2024). "In addition, basophils, eosinophils, and mast cells secrete IL-31 and have the potential to be associated with chronic pruritus." (PMID 38672221, 2024). "IL-31 has been widely implicated in CTCL-associated pruritus in patients." (PMID 36520531, 2023). "Although pruritus provoked by IL-31 may occur independently of mast cells, IL-4 causes overexpression of IL-31 in lymphocytes and mast cells." (PMID 36983094, 2023). "Furthermore, cytokines like IL‐4 and IL‐31 can sensitize peripheral nerves causing them to mediate pruritus sensation." (PMID 37506153, 2023). "Pruritus is associated with increased levels of interleukin-31 (IL-31)." (PMID 33918305, 2021). "Targeting the IL-31 signal may thus be a promising strategy for improving the pruritus associated with diverse skin diseases." (PMID 33924978, 2021). "Recently, it was reported that the IL-31 receptor is expressed in the peripheral nerves of mice and humans, suggesting that IL-31 secreted by Th2 cells may influence right peripheral nerves, triggering the pruritus linked to atopic dermatitis (AD)." (PMID 34118946, 2021). "Another study on mice revealed that IL-31 promotes nerve elongation and branching in vitro and in vivo, which may play a role in pruritus associated with AD, possibly in other pruritic conditions with elevated IL-31 levels as well." (PMID 34209560, 2021).
Pruritus (continued). "Nemolizumab, which targets the pruritogenic cytokine IL-31, has previously shown efficacy against moderate-to-severe pruritus associated with atopic dermatitis; thus, this phase II study aimed to evaluate the efficacy and safety of nemolizumab in hemodialysis patients with UP." (PMID 33754202, 2021). "Also, IL-31 mRNA had a key role in pruritus since it high levels in pathologies intimately linked to it: atopic dermatitis, allergic contact dermatitis and prurigo nodularis." (PMID 34118946, 2021). "In addition, IL-31 was not only strongly associated with pruritus in AD but also exhibited synergy with the H4 receptor, thus aggravating pruritus and skin lesions." (PMID 34970141, 2021). "Increased IL-31 levels and excessive cutaneous sensory innervation are observed in AD patients and AD models including Nc/Nga mice, leading to lowered the pruritus threshold and causing severe pruritus and dermatitis." (PMID 33539470, 2021). "The fact that IL-31 is specifically associated with pruritus in atopic dermatitis and the expression of IL-31 receptors in the CNS raises the suggestion that the pruritus caused by IL-31 might also arise within the CNS itself." (PMID 32204450, 2020). "IL-31 has been known to act as a strong pruritus-inducing agent; however, the underlying mechanism remains unclear." (PMID 30901835, 2019). "We have previously shown that Th2 type cytokines are also elevated in the skin of DH patients, thereby allowing speculation about a possible role of IL-31 in the associated pruritus." (PMID 31244841, 2019). "IL-31 is a T-cell derived cytokine implicated in pruritus in AD, yet the mechanism controlling IL-31 production remains unknown." (PMID 28067314, 2017). "We examined the expression and secretion of IL-31 and IL-6 in microglia and our findings suggest that the elevation of IL-31 and IL-6 levels in CNS could play a direct role in exciting other cells of CNS to cause pruritus." (PMID 40443235, 2025). "Moreover, intradermal administration of IL-31 also causes severe pruritus in normal mice." (PMID 33539470, 2021). "Thus, IL-31 is a T-cell derived cytokine closely associated with pruritus in AD patients." (PMID 28067314, 2017). "Nemolizumab demonstrates efficacy against pruritus and eczema by inhibiting IL-31 signaling in patients with atopic dermatitis." (PMID 41853463, 2026). "These pathways include cytokines, such as IL-4, IL-13, IL-31, and TSLP, and chemokines, such as CCL1, CCL13, and CCL17, which have been implicated in barrier disruption, pruritus, and immune cell recruitment in AD." (PMID 41583462, 2025). "In particular, TSLP, an epithelial cell-derived cytokine, is known to activate dendritic cells and promote Th2 polarization, while IL-31 is directly involved in the induction of pruritus and skin barrier disruption." (PMID 40959436, 2025). "IL-31, produced by Th2 cells, is increasingly recognized as a critical mediator of pruritus in parasitic dermatoses." (PMID 41226755, 2025). "Targeting the IL-31/IL-33 axis represents an emerging therapeutic option, e.g., nemolizumab (anti-IL-31RA) significantly reduces pruritus and AD symptoms in clinical trials." (PMID 41155460, 2025). "IL-31 and Pruritus Modulation: IL-31, a cytokine produced mainly by Th2 cells, is a critical mediator of pruritus via direct action on sensory neurons." (PMID 41226755, 2025). "In psoriasis, pruritus involves Substance P, IL-2, calcitonin gene-related peptide (CGRP), μ-opioid receptors (OPRM), and κ-opioid receptors (OPRK), while in AD pruritus is linked to thymic stromal lymphopoietin (TSLP), CGRP, IL-4, IL-13, and IL-31." (PMID 39859462, 2025). "In particular, IL-31 directly induces pruritus and increases in the lesional skin and serum of AD patients)." (PMID 40109398, 2025). "Therapies targeting neurobiomarkers of ACD, including IL-31 and TRPV1 also show promise in reducing ACD- associated pruritus." (PMID 40181807, 2025).